ENSG00000243501 (novel protein)
Gene: Protein-coding gene on chromosome 6 (73,209,746 to 73,263,196, reverse strand). Ensembl gene ENSG00000243501.
Genetic constraint (gnomAD): Missense variants: 210 observed, 208.68 expected, observed/expected ratio (o/e) 1.01, 90% interval 0.9 to 1.13. Synonymous variants: 64 observed, 70.37 expected, observed/expected ratio (o/e) 0.91, 90% interval 0.74 to 1.12.